LRRC59 (leucine rich repeat containing 59)
Description:
Required for nuclear import of FGF1, but not that of FGF2. Might regulate nuclear import of exogenous FGF1 by facilitating interaction with the nuclear import machinery and by transporting cytosolic FGF1 to, and possibly through, the nuclear pores.
Synonyms: p34; PRO1855; FLJ21675
Tractability: Antibody: UniProt predicts a signal peptide or a membrane-spanning region. PROTAC: ubiquitination databases record sites on it; its protein half-life has been measured.
Gene: Protein-coding gene on chromosome 17 (50,375,059 to 50,398,227, reverse strand). Ensembl gene ENSG00000108829.
Subcellular location: Microsome membrane; Endoplasmic reticulum membrane; Nucleus envelope
Subcellular location (Human Protein Atlas): Endoplasmic reticulum
Gene Ontology:
Molecular function: cadherin binding; protein binding; RNA binding
Biological process: intracellular signal transduction
Cellular component: endoplasmic reticulum; membrane; mitochondrial nucleoid; cytoplasm; endoplasmic reticulum membrane; nuclear envelope
Genetic constraint (gnomAD): Loss-of-function variants: 18 observed, 34.15 expected, observed/expected ratio (o/e) 0.53, 90% interval 0.36 to 0.78. The upper end of that interval is the gene's LOEUF score, 0.78, which puts it in group 3 of 6, group 1 being the genes least tolerant of losing a copy. Missense variants: 330 observed, 405.53 expected, observed/expected ratio (o/e) 0.81, 90% interval 0.74 to 0.89. Synonymous variants: 138 observed, 168.1 expected, observed/expected ratio (o/e) 0.82, 90% interval 0.71 to 0.95.
Homologues: Orthologues: chimpanzee LRRC59 (100% identical), macaque LRRC59 (99% identical), rabbit LRRC59 (97% identical), mouse Lrrc59 (95% identical), rat Lrrc59 (94% identical), dog LRRC59 (94% identical), pig LRRC59 (93% identical), guinea pig LRRC59 (92% identical), tropical clawed frog lrrc59 (55% identical).
Diseases named in the same sentence as LRRC59 in open-access papers:
LRRC59 is named in the same sentence as 20 diseases in open-access papers, as found by Europe PMC text mining. Sharing a sentence is not in itself a finding about the gene and the disease. The quoted sentences say what the papers report.
breast carcinoma (6 papers, 2016 to 2023). "LRRC59 is associated with a significantly poorer prognosis in breast cancer." (PMID 31387239, 2019). "Research has demonstrated a correlation between alterations in LRRC59 expression and the metastatic and invasive potential of breast cancer cell lines." (PMID 37829346, 2023). "In another study, the migratory and metastatic potential of breast cancer is also correlated with another candidate protein, Leucine-rich-repeat-containing protein 59 (LRRC59), uncovered specially in the exosomal cargo derived from dTGFBR2 cells." (PMID 28376875, 2017). "In previous study, a total of 21 proteomic signatures regulated by HMGA1 in breast cancer were reported, and three of them (KIFC1, LRRC59, and TRIP13) were verified to promote breast cancer progression." (PMID 33648560, 2021). "For instance, high LRRC59 expression is closely related to poor survival in LUAD patients and an aggressive phenotype of breast cancer." (PMID 33816266, 2021). "By interrogating a breast cancer gene expression data set (GOBO data set), we obtained the expression of KIFC1, LRRC59, and TRIP13 genes for tumor samples stratified according to HU and PAM50 subtypes, ER status, and histological grade." (PMID 26527623, 2016).
glioma (2 papers, 2021 to 2022). A benign or malignant brain and spinal cord tumor that arises from glial cells (astrocytes, oligodendrocytes, ependymal cells). "Curiously, overexpression of CD26 and LRRC59 has been associated with human glioma stem cells stemness and with invasion and poor prognosis in lung adenocarcinoma, respectively." (PMID 34685551, 2021).
lung adenocarcinoma (2 papers, 2021 to 2023). A carcinoma that arises from the lung and is characterized by the presence of malignant glandular epithelial cells. "Furthermore, It is reported that a strong correlation between elevated LRRC59 expression levels and the survival rate of individuals with lung adenocarcinoma (LUAD) and demonstrated that reducing LRRC59 expression could considerably suppress the migration and invasive capabilities of LUAD cells." (PMID 37829346, 2023).
lung carcinoma (2 papers, 2022 to 2023). "MRPL12 is mainly associated with mitochondrial energy supply and the gene LRRC59 is reported to be associated with poor prognosis in lung cancer and is involved in the cell proliferation process." (PMID 35844396, 2022). "Recent studies have demonstrated that LRRC59 is associated with TNM stage, LNM, histological differentiation, and poor prognosis of lung cancer." (PMID 37706625, 2023).
prostate carcinoma (2 papers, 2019 to 2023). A carcinoma that arises from epithelial cells of the prostate gland. "LRRC59 has been shown to be a binding transporter of the cellular inhibitor PP2A (CIP2A) in prostate cancer, and its fusion transcripts are present in various malignancies such as ovarian, esophageal, and prostate cancers." (PMID 37706625, 2023). "Additionally, LRRC59 has been shown to transport CIP2A (cancer inhibitor of PP2A) into the nucleus, disrupting mitotic checkpoints and deregulating the cell cycle in prostate cancer cells." (PMID 31387239, 2019).
viral infections (2 papers, 2022). "LRRC59 was identified as a vital positive regulator of type I IFN signaling upon virus infection and acted role in innate antiviral responses." (PMID 36591247, 2022). "Hence, the higher expression of LRRC59 in control lymphocytes after PWM stimulation can provoke the comprehensive host’s defenses upon viral infections." (PMID 35225986, 2022). "LRRC59 is a positive regulator of type I IFN signaling, thereby provoking the comprehensive host defenses upon viral infections." (PMID 35225986, 2022).
bladder cancer (1 paper, 2023). "Correlation of LRRC59 expression with clinicopathologic features in 408 patients with bladder cancer (BC)." (PMID 37706625, 2023). "Leucine‐rich repeat‐containing protein 59 (LRRC59) is an endoplasmic reticulum membrane protein involved in various cancers, but its role in bladder cancer (BC) has not been reported." (PMID 37706625, 2023).
cholangiocarcinoma (1 paper, 2023). A carcinoma that arises from the intrahepatic biliary tree (intrahepatic cholangiocarcinoma) or from the junction, or adjacent to the junction, of the right and left hepatic ducts (hilar cholangiocarcinoma). "Differential expression of LRRC59 in pan‐cancers was analyzed based on TIMER database, and the result showed that LRRC59 expression was elevated in bladder, breast, colon cancers, and cholangiocarcinoma." (PMID 37706625, 2023).
hepatocellular carcinoma (1 paper, 2024). A malignant tumor that arises from hepatocytes. "Further, we validated the biological functions of LRRC59 in hepatocellular carcinoma (HCC)." (PMID 38738999, 2024).
Hyperglycemia (1 paper, 2024). An increased concentration of glucose in the blood. "LRRC59 was essential for the hyperglycemia-induced nuclear translocation of KHK-A and cell migration." (PMID 38200154, 2024).
insulinoma (1 paper, 2023). "Interestingly, integral membrane ER resident RBPs (e.g., LRRC59, RPN1, TRAPα) consistently displayed higher RNA-bound protein abundance in rat insulinoma (pancreatic β) cells (832/13) without a comparable change in total abundance." (PMID 37735163, 2023).
liver cancer (1 paper, 2024). An epithelial or non-epithelial malignant neoplasm that arises from the liver. "Survival analysis and prediction showed that patients with high LRRC59 expression had shorter survival times in liver cancer." (PMID 38738999, 2024).
melanoma (1 paper, 2024). A malignant, usually aggressive tumor composed of atypical, neoplastic melanocytes. "In the GSE91061 cohort (Melanomas), the AUC value was 0.349, which meant LRRC59 expression was higher in the immunotherapy resistance group (PD/SD)." (PMID 38738999, 2024).
urothelial carcinoma (1 paper, 2023). A malignant neoplasm derived from the transitional epithelium of the urinary tract (urinary bladder, ureter, urethra, or renal pelvis). "Another study found that LRRC59 overexpression promoted urothelial carcinoma cell proliferation and invasion through ER stress." (PMID 37706625, 2023).
cancer (6 papers, 2019 to 2025). A tumor composed of atypical neoplastic, often pleomorphic cells that invade other tissues. "In this study, we conducted a comprehensive analysis of LRRC59 in pan-cancer, detecting its expression and the associations with prognosis, TMB, tumor metabolism, and chemotherapy sensitivity." (PMID 38738999, 2024). "Overall, we revealed that LRRC59 exhibits abnormal expression in cancer tissues and holds high diagnostic and prognostic value in this study." (PMID 38738999, 2024). "In summary, LRRC59 is significantly upregulated in most cancers and demonstrates high diagnostic efficacy." (PMID 38738999, 2024). "Together these data argue that LRRC59, LEMD2, and CHMP7 together control repair of MN and accumulation of DNA damage in ruptured MN, a major pathophysiological event associated with cancer progression." (PMID 41387506, 2025). "We propose that altered LRRC59 levels and deregulated nuclear transport coordinately compromise NE repair, driving genome instability and cancer development." (PMID 41387506, 2025). "In conclusion, LRRC59 and other hits from our proteome provide key insights into NE rupture-repair processes, but also inroads to tailored treatment of cancer and other diseases characterized by compromised nuclear stability." (PMID 41387506, 2025). "Our enrichment analysis results revealed that LRRC59 was an important gene involved in protein synthesis and degradation within cancer cells." (PMID 38738999, 2024). "In this study, we conducted a comprehensive bioinformatics analysis of LRRC59 using multiple public databases, aiming to systematically determine its expression patterns, prognostic value, and potential functions in pan-cancer." (PMID 38738999, 2024). "Some studies have revealed that LRRC59 was overexpressed in several cancers and promoted tumor progression." (PMID 38738999, 2024). "LRRC59 has also been shown in some studies to be significantly upregulated in several cancer tissues and to be related to a poor prognosis." (PMID 38738999, 2024). "Analysis of the TCGA pan-cancer dataset in the cBioPortal database revealed genetic alterations of LRRC59 in multiple cancers." (PMID 38738999, 2024). "Our analysis of LRRC59 in relation to pan-cancer immune infiltration and immunotherapy reveals a positive correlation between LRRC59 expression and TIM-3 and TIGIT, while a negative correlation with LAG-3 and PDCD1." (PMID 38738999, 2024). "Although our study illustrates the multiple roles of LRRC59 in pan-cancer, it does have some limitations." (PMID 38738999, 2024). "In the TCGA-LIHC dataset, paired expression analysis revealed that the expression of LRRC59 in cancer tissues is elevated significantly." (PMID 38738999, 2024). "FBXO46 plays a role in cancer biogenesis and LRRC59 promotes angiogenesis and can fuel tumor growth." (PMID 31387239, 2019). "Secondly, while our study may serve as a reference for future research, we did not conduct in-depth experiments to delve into the biological functional processes and molecular mechanisms about LRRC59 in pan-cancer." (PMID 38738999, 2024). "In summary, our research suggests that LRRC59 may serve as a potential novel prognostic marker and therapeutic target in pan-cancer." (PMID 38738999, 2024). "Additionally, we elucidated the role of LRRC59 in human cancer progression and treatment resistance through drug sensitivity analysis, enrichment analysis, mutation analysis, and immune analysis." (PMID 38738999, 2024). "Therefore, LRRC59 holds promise as a novel biomarker for pan-cancer diagnosis and prognosis." (PMID 38738999, 2024). "Finally, the validation in HCC demonstrates LRRC59 is significantly overexpressed in cancer tissue and cell lines, and its knockdown inhibits cell proliferation and migration, promotes cell apoptosis, induces cell cycle arrest, and enhances the sensitivity to immunotherapy in HCC cells." (PMID 38738999, 2024).
cancer (continued). "Finally, cell function experiments demonstrated that the knockdown of LRRC59 in COAD cell lines substantially increased cancer cell proliferation and invasion, which was contrary to previous studies of LRRC59 in LUAD, suggesting that LRRC59 plays a different mechanism of action in LUAD and COAD." (PMID 37829346, 2023). "Similar findings were obtained from the analysis using Sangerbox, indicating that high LRRC59 expression was closely related to shorter DSS and PFS in various cancers." (PMID 38738999, 2024). "LRRC59 promotes cancer progression by regulating the nuclear transport of exogenous FGF1, and accelerates cancer cells proliferation and metastasis in various cancers." (PMID 38738999, 2024). "The analysis results showed that LRRC59 expression was negatively correlated with ESTIMATE Score in most cancers, indicating a positive correlation with tumor purity in pan-cancer." (PMID 38738999, 2024). "And our prognosis analysis also revealed a negative correlation between LRRC59 expression levels and the prognosis of cancer patients in various types of cancer." (PMID 38738999, 2024). "As some cancers lacked corresponding adjacent normal tissue data in the TCGA dataset, we analyzed LRRC59’s expression using the GEPIA2 database for a comprehensive exploration." (PMID 38738999, 2024). "LRRC59 appears to be a potential biomarker in certain cancers, however, no study has performed an in-depth pan-cancer analysis of LRRC59 until now." (PMID 38738999, 2024).
tumor (6 papers, 2016 to 2024). "LRRC59 is negatively correlated with immune cell infiltration, tumor purity estimation, and immune checkpoint genes." (PMID 38738999, 2024). "Our findings assess the role of LRRC59 in tumor immunity, providing valuable insights for its potential as a novel target in tumor immunotherapy." (PMID 38738999, 2024). "The prediction results of biological information showed that OS of the patients with high LRRC59 expression was poorer, suggesting that LRRC59 plays a tumor‐promoting role in BC progression." (PMID 37706625, 2023). "The findings revealed that the intensity of LRRC59 immunohistochemical staining was higher in tumor cells compared to normal tissues, suggesting a significant upregulation of LRRC59 expression in tumor tissues compared to normal colon tissues." (PMID 37829346, 2023). "The aim of this study was to clarify the clinicopathologic characteristics of BC and explore the expression profile of LRRC59, its prognostic significance and role in BC tumor cell proliferation and metastasis." (PMID 37706625, 2023). "Next our immune infiltration found that LRRC59 correlated with multiple tumor‐infiltrating immune cells, such as naive CD4 T cells, gamma delta T cells, NK cells, and Tregs." (PMID 37706625, 2023). "By analyzing the differential expression of LRRC59 in tumor and healthy tissues, it was found that the LRRC59 level was considerably elevated in tumor tissues (***p< 0.001)." (PMID 37829346, 2023). "Finally, T cell-mediated tumor cell-killing assay was performed to detected the role of LRRC59 in attenuating the efficacy of immunotherapy, the results showed that LRRC59 knockdown enhances the efficacy of immunotherapy strongly." (PMID 38738999, 2024). "Although LRRC59 was not part of the 4 gene prognostic score it showed higher expression in tumor tissue and was found to be associated with stage and overall survival." (PMID 31387239, 2019). "Among 17 genes that were included in this panel, the expression of YWHAB, MCM4, LRRC59 and FBXO46 was found to be elevated in tumor tissue compared to normal." (PMID 31387239, 2019). "We found that LRRC59 and STIP1 were dysregulated between HNSCC tumor tissues and normal tissues." (PMID 33816266, 2021). "YWHAB, LRRC59 and MCM4 was significantly overexpressed in tumor tissue (p < 0.05)." (PMID 31387239, 2019).
LRRC59 also shares sentences with these, for which no sentence is quoted: colon cancers (1 paper); invasive ductal carcinoma (1); invasive lobular carcinoma (1); Salmonella Infections (1).